ZBED8L (ZBED8 like)
Synonyms: FAM200A; C7orf38; FLJ36794; DKFZp727G131
Tractability: Antibody: UniProt predicts a signal peptide or a membrane-spanning region. PROTAC: ubiquitination databases record sites on it.
Gene: Protein-coding gene on chromosome 7 (99,546,300 to 99,559,392, reverse strand). Ensembl gene ENSG00000221909.
Subcellular location: Membrane
Gene Ontology:
Molecular function: protein binding
Cellular component: membrane
Genetic constraint (gnomAD): Loss-of-function variants: 26 observed, 45.59 expected, observed/expected ratio (o/e) 0.57, 90% interval 0.42 to 0.79. The synonymous counts are far from expectation, so gnomAD's model fits this gene poorly and the ratio says little. Missense variants: 606 observed, 699.04 expected, observed/expected ratio (o/e) 0.87, 90% interval 0.81 to 0.93. Synonymous variants: 206 observed, 258 expected, observed/expected ratio (o/e) 0.8, 90% interval 0.71 to 0.9.
Homologues: Orthologues: chimpanzee FAM200A (99% identical), macaque FAM200A (96% identical), dog FAM200A (87% identical), pig FAM200A (64% identical). Paralogues in human: ZBED11 (76% identical), SCAND3 (36% identical), ZBED5 (33% identical), ZBED8 (29% identical), EPM2AIP1 (21% identical), THAP12 (14% identical), ZMYM4 (12% identical), ZMYM6 (11% identical), ZMYM3 (10% identical), ZMYM2 (10% identical), GTF2IRD1 (9% identical), ZMYM1 (9% identical), and 6 more.